ENC1 (ectodermal-neural cortex 1)
Diseases named in the same sentence as ENC1 in open-access papers (continued):
Sharing a sentence is not in itself a finding about the gene and the disease.
Insulin resistance (1 paper, 2015). Increased resistance towards insulin, that is, diminished effectiveness of insulin in reducing blood glucose levels. "The positive correlation between ENC1 expression and ERK phosphorylation in response to insulin suggests a possible mechanism for higher cancer risk in patients with insulin resistance." (PMID 26202599, 2015).
invasive breast carcinoma (1 paper, 2020). A carcinoma that infiltrates the breast parenchyma. "Thus, we supposed that ENC1 could be a possible therapeutic target among invasive breast cancer." (PMID 32618411, 2020).
medulloblastoma (1 paper, 2018). A malignant, invasive embryonal neoplasm arising from the cerebellum. "ENC1, Ectodermal‐Neural Cortex 1, a nuclear matrix protein, is abundantly expressed in the brain and up‐regulated in human medulloblastoma specimen." (PMID 30098229, 2018).
meningioma (1 paper, 2016). A generally slow growing tumor attached to the dura mater. "The authors found four genes linked to the Wnt signalling: beta-catenin (CTNNB1), the regulatory subunit of cyclin-dependent kinase 5 (CDK5R1), ectodermal-neural cortex 1 (ENC1) and cyclin D1 (CCND1), with the increased expression in meningiomas examined by microarray." (PMID 27429002, 2016).
myelofibrosis (1 paper, 2021). A partial or complete replacement of the bone marrow stroma by fibrous tissue. "Ruxolitinib is a selective JAK1 and JAK2 inhibitor that targets JAK/STAT-associated signaling, exhibiting an effective clinical treatment of myelofibrosis adopted by FDA, which was used to confirm the effect of ENC1 on activation of the JAK2/STAT5/AKT axis in CRC cells." (PMID 33816464, 2021).
myocardial infarction (1 paper, 2020). Gross necrosis of the myocardium, as a result of interruption of the blood supply to the area, as in coronary thrombosis. "Myocardial infarction associated transcript and ectodermal-neural cortex 1 (ENC1) expression was detected by reverse transcription quantitative polymerase chain reaction." (PMID 33551826, 2020). "Myocardial infarction associated transcript could regulate the expression of ENC1, and MYC could bind to the promoter region of ENC1." (PMID 33551826, 2020). "Myocardial infarction associated transcript and ENC1 were upregulated in IA." (PMID 33551826, 2020).
oncocytoma (1 paper, 2020). "However, the ENC1 gene was reported to be negatively related with the invasiveness of human pituitary null cell adenoma and oncocytoma." (PMID 32618411, 2020).
tumor (23 papers, 2004 to 2025). "Then we looked into it further and discovered that ENC1 expression was linked to tumor microenvironment and predicted various immunological checkpoints." (PMID 36531950, 2022). "A cohort study of TCGA dataset showed that overexpression of ENC1 is associated with tumor progression and poor prognosis." (PMID 35818360, 2022). "In contrast, the expression levels of NF-κB regulated genes encoding anti-apoptotic proteins (e.g. BCL-XL, ENC1) are more highly expressed in the invasive rim subpopulation of GBM specimens as compared to their matched tumor core." (PMID 23967279, 2013). "ENC1 is involved in tumor cell angiogenesis, invasion, and metastasis through matrix metalloproteinases, and encourages tumor metastasis through EMT9." (PMID 38177640, 2024). "Overexpression of ENC1 has been correlated with the stage of the tumor and has been used as a prognostic marker for disease-free survival and overall survival." (PMID 38177640, 2024). "Inhibition of ENC1 was found to increase the rate of apoptosis in tumor tissues following radiation treatment." (PMID 38177640, 2024). "Knockdown of ENC1 in mouse xenotransplantation and lung metastasis models inhibits tumor growth and metastasis." (PMID 38177640, 2024). "A nude mouse model of subcutaneous tumor xenotransplantation was developed to investigate the effects of ENC1 downregulation on cancer cells." (PMID 38177640, 2024). "By activating this signaling cascade, ENC1 promotes tumor growth and invasion by facilitating cell proliferation and inhibiting apoptosis." (PMID 39136001, 2024). "Keap1 (KLHL19) and three other members of the KLHL family are linked to tumor genesis: KLHL6, KLHL20, and KLHL37 (ENC1)." (PMID 37109574, 2023). "ENC1 were also overexpressed in UCEC tumor tissues or cell lines, as shown by quantitative real-time PCR and Western blotting." (PMID 36531950, 2022). "According to the GEPIA website, PKM2 and ENC1 were over-expressed in tumor tissues and under-expressed in normal tissues, but NR3C1 was the inverse." (PMID 36531950, 2022). "The changes in tumor growth were plotted on a tumor growth curve which showed that mouse tumor size decreased in the ENC1 shRNA-1 group." (PMID 33816464, 2021). "Western blotting and qRT-PCR verified ENC1 protein and mRNA expression being downregulated in the ENC1 shRNA-1 xenograft tumor group." (PMID 33816464, 2021). "Notably, ruxolitinib could restrict tumor-sphere formation caused by ENC1 overexpression." (PMID 33816464, 2021). "We found that the protein expression of TCF4 and ENC1 in tumor tissues was largely consistent with those in cells." (PMID 34362881, 2021). "The study is a novel proposition with silencing of ENC1, not only significantly reducing the malignant phenotype but also showing a therapeutic reduction in tumor numbers and volumes in vivo." (PMID 33816464, 2021). "We also found that knocking down ENC1 significantly promoted the sensitivity of RaR cells to radiotherapy in vivo and suppressed tumor growth rate." (PMID 34362881, 2021). "Metastatic nodules on the surfaces of mice lungs were confirmed by H&E staining, whereas the expression level of ENC1 in the nodules was also verified by IHC staining, thus concluding that ENC1 knockdown restrains xenograft tumor growth and lung metastasis." (PMID 33816464, 2021). "Mice overexpressing ENC1 had significantly increased tumor burden compared to mice carrying vector cells, as detected by BLI signal detection in the brain and hindlimb." (PMID 34362881, 2021). "When the mouse tumor size in the ENC1 shRNA-1 group was significantly less than the Ctrl-shRNA group, xenograft tumors were isolated and imaged." (PMID 33816464, 2021). "This is exemplified by the AGPS and ENC1 neoepitopes that were detected by MS as being presented on the tumor lines." (PMID 31921104, 2019). "Studies suggest that ENC1 may modulate tumor cell malignancy through reactive oxygen species and various signaling pathways." (PMID 38177640, 2024).
tumor (continued). "Additionally, ENC1 has been found to impact the radiosensitivity of super-enhancer-driver-driven tumor cells, which can have an impact on cancer patient prognosis." (PMID 38177640, 2024). "ENC1 were also overexpressed in tumor tissues or cells, as shown by qRT-PCR and Western blotting." (PMID 36531950, 2022). "Silencing of ENC1 resulted in lesser tumor volumes and fewer numbers of tumors, in vivo." (PMID 33816464, 2021). "In the current study using a combinatorial approach of in vitro and in vivo models, we report that ENC1 expression in CRC is associated with increased cellular proliferation, migration, invasion, and tumor growth, and this was likely mediated through the JAK2-STAT5-AKT axis." (PMID 33816464, 2021). "Moreover, overexpression of TCF4 reduced the apoptosis rate of tumor tissues after radiotherapy in the presence of si-ENC1." (PMID 34362881, 2021). "Additionally, H&E staining results identified tumor morphological characteristics and IHC showed reduced the expression of ENC-1 and Ki-67 in the Ctrl-shRNA group in comparison to xenograft tumor groups." (PMID 33816464, 2021). "The mouse xenograft model was established to prove whether silenced ENC1 could retard tumor growth in vivo." (PMID 33816464, 2021). "Since we used siRNAs to knock down the expression of ENC1 in cells, and the effectiveness of siRNAs decreases with cell replication, we used western blot to detect the expression of ENC1 in tumor tissues, and we found that siENC1 still has the ability to reduce the expression of ENC1." (PMID 34362881, 2021). "Several of the genes upregulated in CTNNB1-mutated tumours have previously been described as overexpressed in CTNNB1-mutated adrenal lesions, regardless of type of hormone production or differentiation level: AFF3, ISM1, NKD1, ENC1 and RALBP131,32." (PMID 31000732, 2019). "Moreover, silencing of ENC1 also enhanced apoptosis rate of tumor tissues after radiotherapy." (PMID 34362881, 2021). "Top differentially suppressed genes as the tumor transformed included SMOC1, BCAN, NES, AIF1L, ENC1, and IGF2 (p < 0.01)." (PMID 39256867, 2024). "In turn, the increased ROS levels and other changes in monocytes induced by ENC1 contribute to the immunosuppressive environment in MDS and promote tumor development." (PMID 38177640, 2024). "For instance, several down-regulated PCGs in the LL-like tumor samples, including SOCS2, CADM2, SH3TC and ENC1, are previously reported as potential tumor suppressors." (PMID 35939448, 2022). "For the two other epitopes identified by MS as presented on KADA tumor MHC-I (AGPS, ENC1), we could unequivocally demonstrate that these epitopes were not recognized by the autologous TIL." (PMID 31921104, 2019).
cancer (19 papers, 2012 to 2025). A tumor composed of atypical neoplastic, often pleomorphic cells that invade other tissues. "In cancer patients, high levels of ENC1 expression have been linked to increased malignancy, metastasis, and a poorer prognosis." (PMID 38177640, 2024). "KLHL members associated with inherited forms of the human disease include KLHL3, KLHL7, KLHL9, KLHL12, and GAN (KLHL16), whereas KLHL6, KEAP1 (KLHL19), KLHL20, and ENC1 (KLHL37) are associated with cancer." (PMID 33897412, 2021). "Further, ENC1 dysregulation and associated malignancies have been confirmed in cancers of prostrate, ovarian, pancreatic, and colon." (PMID 33816464, 2021). "Since ENC1 was associated with various cancers and brain diseases, we intended to investigate the existence of an association between ENC1 and IA." (PMID 33551826, 2020). "In addition to its role in cancer growth and spreading, ENC1 has also been linked to neuronal process development and neural crest cell differentiation." (PMID 38177640, 2024). "ENC1 has been shown to be closely linked to cancer metastasis by modulating the β-catenin pathway." (PMID 38177640, 2024). "Recently, a detailed pan-cancer investigation identified ENC1 (ectodermal-neural cortex 1) as a potential prognostic biomarker for TME and treatment efficacy." (PMID 40732268, 2025). "This article focuses on the relevance of ENC1 in cancer and the potential impact of targeting ENC1 in cancer treatment." (PMID 38177640, 2024). "Given its versatility, it is possible that ENC1’s impact on cancer growth and metastasis is not limited to a single substrate, but rather affects multiple signaling pathways simultaneously." (PMID 38177640, 2024). "Upregulation of ENC1 has been observed in various cancers, including breast, colon, lung, and ovarian cancer." (PMID 38177640, 2024). "Further research is warranted to fully elucidate the therapeutic potential of targeting ENC1 in cancer." (PMID 38177640, 2024). "In this review, we provide an overview of the current knowledge on the relationship between ENC1 and cancer." (PMID 38177640, 2024). "We also summarize the potential of targeting ENC1 for cancer therapy, as its inhibition has been shown to significantly reduce cancer cell invasion, growth, and metastasis." (PMID 38177640, 2024). "Conversely, reducing ENC1 expression via knockout has been shown to significantly inhibit cancer cell invasion, growth, and metastasis, and improve patient prognosis." (PMID 38177640, 2024). "Our subsequent analysis in TCGA-BRCA database revealed a significant augment in ENC1 expression in cancer tissues." (PMID 34362881, 2021). "Four KLHL family members are associated with cancer: KLHL6, KEAP1 (KLHL19), KLHL20, and ENC1 (KLHL37)." (PMID 23676014, 2013). "Finally, we highlight the remaining gaps in our understanding of ENC1’s role in cancer and propose potential directions for future research." (PMID 38177640, 2024). "By understanding the role of ENC1 in cancer development and progression, we can explore new therapeutic approaches that may ultimately improve patient outcomes." (PMID 38177640, 2024). "Given the ability of targeted ENC1 to inhibit cancer cell growth, induce apoptosis, and modulate radiotherapy sensitivity, it may represent a promising new therapeutic strategy for cancer treatment." (PMID 38177640, 2024). "Collectively, the evidence suggests that ENC1 may be a novel target for the development of new therapeutic options for cancer treatment." (PMID 38177640, 2024). "Therefore, 6 of the genes (ENC1, ACAT1, MSTC1, MADCAM1, RPL23 and SNRPB2) were found to be associated with cancer, genetic disorder or reproductive system disease within the same network." (PMID 22280244, 2012). "However, the function of ENC1 in human cancer is still indefinable." (PMID 32618411, 2020).
cancer (continued). "The cancer-promoting proteins (NCBP2, AMD, MER34, ENC1, and COA4) were suppressed, while the secretory glycoprotein (A1BG) and ROS-reducing protein (ASB6) were overexpressed in the treatment group." (PMID 35818360, 2022). "Here, we showed that natural peptides from T. stans inhibited the growth, migration and invasion of A549 cells by suppressing the expression of cancer-promoting proteins (NCBP2, AMD, MER34, ENC1, and COA4)." (PMID 35818360, 2022). "The volcano plot revealed that the cancer-promoting proteins (NCBP2, AMD, MER34, ENC1, and COA4) were down-regulated, while the secretory glycoprotein (A1BG) and ROS-reducing protein (ASB6) were up-regulated in the treatment group." (PMID 35818360, 2022). "Ectodermal neural cortex 1 (ENC1) is an actin-binding protein and has been known to be upregulated in several cancers, but the molecular mechanisms through which it contributes to the pathology of CRC have largely been elusive." (PMID 33816464, 2021). "Eight of these had decreased expression in cancer (KLHL3, KLHL4, KLHL13, KLHL14, KLHL29, KLHL30, KLHL32, and KLHL33) while four genes (ENC1, KLHL12, KLHL17, and KLHL35) had patterns of up-regulated gene expression." (PMID 30647843, 2018). "Additionally, association analysis of CMTM6 mRNA levels with Wnt target genes (TCF4, LEF1, CD-44, MMP14, ENC1, ID2, PPARA, and JAG1) from the cancer genome atlas HNSCC cohort using GEPIA showed a positive correlation (r > 0.2)." (PMID 33434185, 2021). "However, there are currently no clinical trials or studies focused on targeting ENC1 for cancer treatment." (PMID 38177640, 2024). "Interestingly, these two modules contain three common mRNAs (EMILIN1, COL1A2, ENC1) and one of them (COL1A2) is related to cancer, suggesting that these modules (e.g. modules 15 and 17, modules 31 and 32 in OV) with many overlaps of mRNAs are more likely to have similar biological functions." (PMID 30732558, 2019).
gynecological neoplasms (1 paper, 2024). "In this paper, we review studies on ENC1 in gastrointestinal malignancies, gynecological neoplasms, respiratory system and hematological system tumors." (PMID 38177640, 2024).
ENC1 also shares sentences with these, for which no sentence is quoted: astrocytomas (2 papers); neuroblastoma (2); schizophrenia (2); achondroplasia (1); adrenal tumours (1); adult-onset Still disease (1); autism (1); benign tumors (1); brain cancer (1); brain diseases (1); colorectal (1); dementia (1); depression (1); endometrioid adenocarcinoma (1); epilepsy (1); gastric cancer (1); genetic disorder (1); Hypertension (1); hypothyroidism (1); infection (1); keratosis (1); kidney diseases (1); lymph node metastasis (1); mental disorder (1); metabolic disorder (1); myelodysplastic syndrome (1); nervous system tumors (1); pancreatic cancer (1); personality disorder (1); prostate carcinoma (1).
A further 6 diseases each share a sentence with ENC1 in 1 paper.